GRM5P1 (GRM5 pseudogene 1)
Gene: Transcribed unprocessed pseudogene on chromosome 11 (49,560,818 to 49,810,417, forward strand). Ensembl gene ENSG00000205035.
Diseases named in the same sentence as GRM5P1 in open-access papers:
GRM5P1 is named in the same sentence as 1 disease in open-access papers, as found by Europe PMC text mining. Sharing a sentence is not in itself a finding about the gene and the disease. The quoted sentences say what the papers report.
Obesity (1 paper, 2023). Accumulation of substantial excess body fat. "We also found a 1.59 kb copy number deletion (dbVar ID: nssv15803200, 11:49759283–49,760,872) within intron 2 of GRM5P1(GRM5 pseudogene 1) associated with early obesity." (PMID 38110883, 2023).